ZNF45 (zinc finger protein 45)
Description:
May be involved in transcriptional regulation.
Synonyms: KOX5; ZNF13
Tractability: PROTAC: UniProt records ubiquitination sites on it; ubiquitination databases record sites on it.
Gene: Protein-coding gene on chromosome 19 (43,910,549 to 43,935,306, reverse strand). Ensembl gene ENSG00000124459.
Subcellular location: Nucleus
Subcellular location (Human Protein Atlas): Nucleoplasm
Pathways (Reactome):
Gene expression (Transcription): Generic Transcription Pathway
Gene Ontology:
Molecular function: DNA-binding transcription factor activity
Biological process: regulation of DNA-templated transcription
Cellular component: nucleoplasm; nucleus
Genetic constraint (gnomAD): Loss-of-function variants: 5 observed, 16.61 expected, observed/expected ratio (o/e) 0.3, 90% interval 0.16 to 0.63. The upper end of that interval is the gene's LOEUF score, 0.63, which puts it in group 2 of 6, group 1 being the genes least tolerant of losing a copy. Missense variants: 691 observed, 838.64 expected, observed/expected ratio (o/e) 0.82, 90% interval 0.77 to 0.88. Synonymous variants: 266 observed, 287.65 expected, observed/expected ratio (o/e) 0.92, 90% interval 0.84 to 1.02.
Homologues: Orthologues: chimpanzee ZNF45 (99% identical), macaque ZNF45 (88% identical), dog ZNF45 (85% identical), pig ZNF45 (85% identical), guinea pig ZNF45 (82% identical), rabbit ZNF45 (75% identical), rat Zfp94l1 (64% identical), mouse Zfp94 (54% identical), rat Zfp94 (52% identical). Paralogues in human: ZNF234 (48% identical), ZNF226 (47% identical), ZNF112 (45% identical), ZNF229 (42% identical), ZNF235 (41% identical), ZNF227 (40% identical), ZNF224 (39% identical), ZNF658 (38% identical), ZNF33B (38% identical), ZNF606 (38% identical), ZNF28 (37% identical), ZNF726 (37% identical), and 164 more.
Diseases named in the same sentence as ZNF45 in open-access papers:
ZNF45 is named in the same sentence as 7 diseases in open-access papers, as found by Europe PMC text mining. Sharing a sentence is not in itself a finding about the gene and the disease. The quoted sentences say what the papers report.
alcohol use disorder (1 paper, 2025). "Whole‐exome sequencing of 83 alcohol use disorder patients identified 106,525 SNVs and 19,826 InDels, revealing six genes (CNTNAP3, ZNF683, ALDH2, CCHCR1, ZNF45, ESRRA) with deleterious mutations through comprehensive bioinformatics analysis." (PMID 40730494, 2025).
Alzheimer disease (1 paper, 2025). A progressive, neurodegenerative disease characterized by loss of function and death of nerve cells in several areas of the brain leading to loss of cognitive function such as memory and language. "A whole‐transcriptome splicing association study found that ZNF45 was associated with susceptibility to Alzheimer's disease." (PMID 40730494, 2025).
Obesity (1 paper, 2025). Accumulation of substantial excess body fat. "ZNF45 gene expression was negatively associated with BMI, suggesting that this gene is associated with obesity and metabolic disorders." (PMID 40730494, 2025).
schizophrenia (1 paper, 2025). A major psychotic disorder characterized by abnormalities in the perception or expression of reality. "GWAS of developmental dyslexia (DD) revealed that ZNF45 was expressed lower in schizophrenia patients than in the controls." (PMID 40730494, 2025).
ZNF45 also shares sentences with these, for which no sentence is quoted: breast carcinoma (1 paper); glioblastoma (1); metabolic disorders (1).